VCAM1 (vascular cell adhesion molecule 1)
Diseases named in the same sentence as VCAM1 in open-access papers (continued):
Sharing a sentence is not in itself a finding about the gene and the disease.
endothelial dysfunction (continued). "Chromium could also reduce reactive oxygen species (ROS) and TNF-α, inhibit the expression of NF-kB, and decrease the expression of vascular cell adhesion molecule 1 (VCAM-1), thereby improving endothelial dysfunction." (PMID 38730326, 2024). "AKT1, TNF-α, VCAM1, ICAM1, and NOS3 might be the key targets of the anti-endothelial dysfunction activity of biochanin A, and the key pathways might be PI3K-Akt and TNF signaling pathways." (PMID 38195507, 2024). "The JAK/STAT3 pathway works closely with leukemia inhibitory factor (LIF) to induce inflammation and endothelial dysfunction, characterized by increased levels of intercellular adhesion molecule-1 (ICAM-1) and vascular cell adhesion molecule-1 (VCAM-1), all of which are hallmarks of preeclampsia." (PMID 39596234, 2024). "Biochanin A possibly prevents endothelial dysfunction via a complex network structure with multiple targets and pathways, among which AKT1, TNF-α, NOS3, ICAM-1, and VCAM-1 may be the key targets, according to network pharmacological analysis results." (PMID 38195507, 2024). "Thus, further studies detecting endothelial dysfunction markers such as ZO-1, ICAM-1, and VCAM-1 in the aortic roots by immunofluorescence staining are recommended." (PMID 38839811, 2024). "Also, high AUC for Ang 2:Ang1, Ang 2:Tie 2, ICAM1:VCAM-1, and VEGFA: Ang 2 ratios suggest endothelial dysfunction and instability, key factors in SCD and angiogenesis." (PMID 39749215, 2024). "The anti-atherosclerotic action of SAMB may also be attributed to its inhibitory role on endothelial dysfunction, which was possibly supported by the suppressive impact of SAMB on VCAM-1 expression in endothelial cells." (PMID 38839811, 2024). "The study of pregnant women found that 14-day exposure to PM10 but not PM2.5 significantly increased levels of soluble vascular cell adhesion molecule 1 (sVCAM-1), a marker of endothelial dysfunction, providing evidence of a mechanism." (PMID 38978038, 2024). "It was also recently proposed that MOTS-c may also improve endothelial dysfunction via the MAPK/NF-κB pathway, which is involved in endothelial dysfunction by regulating the surface expression of adhesion molecules such as VCAM-1 and ICAM-1." (PMID 36670507, 2023). "As GDM is associated with endothelial dysfunction, we also assessed whether GDM might alter the expression of endothelial dysfunction markers ICAM1 and VCAM1." (PMID 37893034, 2023). "Indeed, the role of TMAO in the modulation of factors strictly related to the development of endothelial dysfunction, such as nitric oxide, adhesion molecules (ICAM-1, VCAM-1, and selectins), and IL-6, has been widely accepted." (PMID 36982880, 2023). "On the other hand, overexpression of miR125a resulted in a decline in ICAM-1 and VCAM-1 expression in human brain microvessel endothelial cells, and our result showed that miR125a positively correlated with markers of endothelial dysfunction (i.e. ICAM-1 and VCAM-1)." (PMID 37917636, 2023). "Furthermore, exposure to HG + IS led to upregulation of adhesion molecules SELE, VCAM1, ICAM-1 in HUVEC, while incubation of DKD-MSCcm attenuated mRNA expression, suggesting that DKD-MSCcm prevents endothelial dysfunction." (PMID 36949528, 2023). "In addition, LIF can induce inflammation and endothelial dysfunction by increasing the expression of intercellular adhesion molecule-1 (ICAM-1) and vascular cell adhesion molecule-1 (VCAM-1) through the JAK/STAT3 pathway." (PMID 38235138, 2023). "Endothelial dysfunction is an early indicator of AS, characterized by overexpression of adhesion molecules, including intercellular adhesion molecule-1 (ICAM-1) and vascular cell adhesion molecule-1 (VCAM-1)." (PMID 37325477, 2023).
endothelial dysfunction (continued). "Studies have shown that the ACE2-Ang II axis can induce the infiltration of macrophages and secretion of certain cytokines, including IL-6, CCL2, vascular cell adhesion molecule 1 (VCAM-1), and E-selectin, to induce endothelial dysfunction, thrombin formation, and impaired fibrinolysis." (PMID 35464491, 2022). "To investigate the TRC105 effect on biomarkers of inflammation and endothelial dysfunction, we measured protein levels of the cell adhesion molecules VCAM-1 and P-selectin in HAoECs exposed to TRC105 with or without 7K treatment." (PMID 36160139, 2022). "Leptin also induces endothelial dysfunction (ED) by upregulating vascular adhesion molecules such as intercellular adhesion molecule-1 (ICAM-1) and vascular cell adhesion molecule-1 (VCAM-1) through AKT/GSK3β and Wnt/β-catenin signaling pathways, promoting renal inflammation and vascular remodeling." (PMID 36726470, 2022). "Furthermore, PCB can regulate important markers of oxidative stress and endothelial dysfunction, such as eNOS, p22 NOX subunit, and vascular cell adhesion molecule-1 (VCAM-1)." (PMID 35726224, 2022). "In addition, in patients with MetS, the combination of the two can reduce the plasma levels of plasminogen activator inhibitor-1 and vascular cell adhesion molecule-1 (VCAM-1), both of which are vascular inflammation markers of endothelial dysfunction." (PMID 35656118, 2022). "Therefore, VCAM-1, ICAM-1, and E-selectin are considered as important markers of endothelial dysfunction." (PMID 34123418, 2021). "High glucose could increase the expression of monocyte chemoattractant protein-1 (MCP1) and vascular cell adhesion molecule-1 (VCAM-1), thus enhance the monocyte-endothelial cell interaction and promote the atherogenic process and endothelial dysfunction." (PMID 34521385, 2021). "In this work, endothelial dysfunction was induced in HFD fed ApoE-/- mice, as demonstrated by the decrease of serum NO level as well as the increase of the adhesion molecule (E-selectin, ICAM-1 and VCAM-1) and chemokine (MCP-1) expression in the aorta." (PMID 34769040, 2021). "Additionally, IFN-α, through miR155, promotes an endothelial dysfunction signature in HUVECs characterized by transcription suppression and the mRNA instability of eNOS and by the upregulation of MCP-1 and VCAM-1 and enhanced neutrophil adhesion." (PMID 33868242, 2021). "There is evidence that the fluctuations in blood glucose levels known as glycemic variability (GV) has correlation with the endothelial dysfunction T2D patients, characterized by increased expression of adhesion (ICAM-1, VCAM-1) and proinflammatory molecules (IL-8, NF-κB)." (PMID 33572702, 2021). "In addition, the sTREM-1 level is positively correlated with biomarkers for endothelial dysfunction (ICAM-1, VCAM-1, and E-selectin) and lactate level, clinical severity index (the maximum 24 h APACHE score and maximum 24 h SOFA score) upon admission." (PMID 34829326, 2021). "Additionally, activated endothelial cells express vascular cell adhesion molecule 1 (VCAM-1) and support leukocyte adhesion, contributing to the pathological endothelial dysfunction seen in P-EC." (PMID 34805227, 2021). "Looking further into the endothelial dysfunction model, all three beta-blockers significantly reduced expression of vascular cell adhesion molecule 1 (VCAM), a critical factor in the inflammatory process involved in the recruitment and migration of leukocytes, and marker of endothelial dysfunction." (PMID 34362171, 2021). "sTREM-1 levels positively correlated with biomarkers for endothelial dysfunction (ICAM-1, VCAM-1, and E-selectin) and lactate level as well as clinical severity index (maximum 24 h APACHE score and Sequential Organ Failure Assessment (SOFA) score) upon admission." (PMID 34829326, 2021).
endothelial dysfunction (continued). "In addition, GSTM1 knockdown induced in vitro upregulation of cell adhesion molecules and markers of endothelial dysfunction, ICAM-1 and VCAM-1, which has also been confirmed in the clinical settings using plasma samples from patients with ESRD." (PMID 33574979, 2021). "Moderate effects were noted on reducing markers of endothelial dysfunction with some reduction in ET-1 observed and no change to VCAM-1." (PMID 33919808, 2021). "Moreover, when endothelial dysfunction occurs in the IR state, the expression of ICAM-1 and VCAM-1 is promoted; thus monocytes adhere to endothelial cells in circulation." (PMID 33628325, 2021). "Indeed, vascular cell adhesion molecule 1 (VCAM-1) and intercellular adhesion molecule 1 (ICAM-1) play an important role in the initiation of inflammation and endothelial dysfunction." (PMID 34940528, 2021). "Increased CRP and reactive oxygen species (ROS) could trigger endothelial dysfunction that can increase the levels of ICAM-1 and VCAM-1, leading to increased monocyte chemoattraction, binding to LDL-molecules and increased risk for cardiovascular disease." (PMID 33269023, 2020). "In addition, expression of VCAM-1, ICAM-1, P-selectin or pNF-κB are induced during inflammation by several stimuli, and these molecules facilitate transmigration of leukocytes during endothelial dysfunction." (PMID 32470058, 2020). "Likewise, an increased levels of ICAM-1, VCAM-1, and selectins in women with GDM are a reflection of endothelial dysfunction contemplating the future metabolic risks via metabolic memory effects." (PMID 33085688, 2020). "Under abnormal WSS, nuclear factor-κB (NF-κB) in cerebral arterial walls upregulates expression of downstream genes, such as monocyte chemoattractant protein 1 (MCP-1) and vascular cell adhesion molecule 1 (VCAM-1) gene, which lead to macrophage infiltration and endothelial dysfunction." (PMID 31849575, 2019). "Des-fluoro-anacetrapib treatment was also associated with decreased bypass grafting-induced endothelial expression of vascular cell adhesion molecule-1 (VCAM-1) and intercellular adhesion molecule-1 (ICAM-1), endothelial dysfunction, and smooth muscle cell (SMC) proliferation in the grafted vein." (PMID 31700015, 2019). "We hypothesized that altitude-related endothelial dysfunction would lead to progressive shedding of ICAM-1, VCAM-1 and VE-cadherin into plasma." (PMID 31369589, 2019). "Complementary experiments to measure plasma biomarkers of inflammation, oxidative stress, and endothelial dysfunction such as resistin, ICAM-1, VCAM-1, and E-selectin could be useful to refine the mechanism of action of MOI." (PMID 31214278, 2019). "Another recent study showed that components of the IL-6 trans-signaling system were significantly elevated in more than 200 subjects with MetS and positively correlated with markers of endothelial dysfunction and arterial stiffness, such as E-selectin, ICAM-1 and VCAM-1." (PMID 31550292, 2019). "In addition, we demonstrated metformin reduced endothelial dysfunction, significantly reducing TNF-α-induced VCAM-1 expression and enhancing whole-blood vessel vasodilation." (PMID 29466360, 2018). "Studies of endothelial dysfunction further showed elevated blood levels of the intercellular adhesion molecule ICAM1 in patients with lacunar infarctions, whereas VCAM1 and P-selectin were increased in cases with WMLs at the periventricular region but not at deep subcortical locations." (PMID 30470258, 2018). "As expected, in the presence of 1 ng/ml TNFα, VCAM-1 expression was induced 300-fold compared to cells with no TNFα indicating significant endothelial dysfunction." (PMID 28500309, 2017). "In conclusion, data presented here show that TMAO is a novel positive regulator of endothelial dysfunction and the effect of TMAO on endothelial dysfunction is partly attributable to activation of PKC/NF-κB, leading to elevated expression of VCAM-1 and monocyte adhesion." (PMID 28153917, 2017).
endothelial dysfunction (continued). "Moreover, Pin1 inhibition prevents diabetes-induced expressions of VCAM-1 and MCP-1 and endothelial dysfunction." (PMID 28300760, 2017). "Moreover, isocarbophos remarkably induced endothelial dysfunction in the middle cerebral artery and the expressions of ICAM‐1 and VCAM‐1 in the posterior cerebral artery." (PMID 26818681, 2016). "Endothelial dysfunction is also accompanied withan increased expression of cell adhesion molecules, such as intercellular adhesion molecule-1 (ICAM-1), vascular cell adhesion molecule-1 (VCAM-1), and inflammatory cytokine secretion." (PMID 26473356, 2015). "A widely popular definition of the endothelial dysfunction includes overexpressing adhesion molecules such as ICAM-1, VCAM-1, E-selectin, and P-selectin in the vascular endothelium as well as physiological changes such as flow-mediated vasodilatation (FMD) or forearm blood flow (FBF)." (PMID 24829798, 2014). "Regarding endothelial dysfunction (ED), vWF, ICAM-1, and VCAM-1 were selected as indicators." (PMID 23671885, 2013). "For these reasons, VCAM-1 is a valid candidate marker to measure endothelial dysfunction in vivo, but its high levels should be considered as an indicator of systemic endothelial dysfunction and not just a local phenomenon." (PMID 24207059, 2013). "Similarly, higher AF was detected in patients with endothelial dysfunction expressed by vWF, ICAM-1, and VCAM-1." (PMID 23671885, 2013). "Recently, microvascular endothelial inflammation has also gained clinical importance in mediating endothelial dysfunction by reducing coronary flow reserve and myocardial perfusion in HFpEF patients via increased expression of endothelial adhesion molecules like ICAM-1 and VCAM-1." (PMID 40072053, 2025). "N. sativa seems beneficial in attenuating VCAM-1 and ICAM-1 levels under different situations; however, additional long-term controlled clinical trials are needed for making concise conclusions about the effect of N. sativa on endothelial dysfunction related biomarkers." (PMID 40365513, 2025). "ox-LDL-induced LOX-1 activation triggers endothelial dysfunction and the expression of atherosclerotic inflammatory genes, such as monocyte chemotactic protein 1 (MCP-1), intercellular adhesion molecule 1 (ICAM-1), and vascular cell adhesion molecule 1 (VCAM-1) in ECs." (PMID 35402552, 2022). "Several studies have assessed endothelial dysfunction usingflow-mediated dilatation (FMD), nitroglycerin-mediated dilation (NMD), andbiomarkers (E-selectin, P-selectin, intercellular adhesion molecule-1 (ICAM-1),and vascular cellular adhesion molecule-1 (VCAM-1))." (PMID 39076622, 2022). "In addition, ADM has been shown to reduce the expression of endothelial dysfunction biomarkers such as intercellular adhesion molecule-1 (ICAM-1) and vascular adhesion molecule-1 (VCAM-1), and inflammatory factors in lymphatic endothelium and VEGF-stimulated human umbilical vein endothelial cells." (PMID 36362188, 2022). "In addition, both sotagliflozin and empagliflozin prevented the Ang II-induced down-regulation of eNOS and formation of NO in response to bradykinin, and the up-regulation of VCAM-1, MCP-1 and tissue factor indicating a determinant role of SGLT1 and 2 in the induction of endothelial dysfunction." (PMID 33726768, 2021). "The decrease in transpulmonary ICAM-1 and VCAM-1 concentrations in PAH children (fold change 0.86 and 0.85, respectively) indicates either intrapulmonary uptake or increased intrapulmonary degradation of these vascular injury mediators that drive endothelial dysfunction." (PMID 34957265, 2021). "This experimental model demonstrated endothelial dysfunction, manifested by the inflammatory cytokine TNF-α as well as by adhesion molecules that are indicators of endothelial damage, such as ICAM-1 (87.6%, 122 ± 9 vs 65 ± 5, p < 0.0001) and VCAM-1 (29.4% 110 ± 10 vs 85 ± 2, p < 0.05)." (PMID 32795274, 2020).
endothelial dysfunction (continued). "In this study, quercetin could inhibit LPS-induced attachment of monocytes to HUVECs by downregulating expressions of VCAM-1 and ICAM-1 in vitro as well as suppress the expression of pro-inflammatory cytokines, which demonstrated the ability of quercetin to ameliorate endothelial dysfunction." (PMID 33425996, 2020). "The content of the circulating adhesion molecule vCAM-1 was positively correlated with the levels of CRP (r = 0.42), leptin (r = 0.31), TNF-a (r = 0.35) and IL-6 (r = 0.52), indicating the participation of proinflammatory molecules in the formation of endothelial dysfunction (p < 0.05)." (PMID 30871567, 2019). "Mitochondrial enzyme arginase type II (Arg-II) is reported to lead to endothelial dysfunction and enhance the expression of endothelial inflammatory adhesion molecules such as intercellular adhesion molecule-1 (ICAM-1) and vascular cell adhesion molecule-1 (VCAM-1)." (PMID 31474872, 2019). "Endothelial dysfunction can also be evaluated by quantifying specific indicators of coagulation such as plasminogen activator inhibitor-1 (PAI-1), markers of inflammation (e.g. ICAM-1 and VCAM-1, or circulating markers derived from the endothelium such as ADMA (asymmetric dimethylarginine)." (PMID 31456040, 2019). "Furthermore, endothelium in the aorta displayed increased VCAM-1 expression compatible with endothelial dysfunction, although there were no changes in the eNOS immunostaining intensity." (PMID 29967661, 2018). "Plasma concentrations of E-selectin, ICAM-1, and VCAM-1 as markers of endothelial dysfunction were proven to predict development of T2D in initially nondiabetic women, and the association was independent of other known risk factors such as subclinical inflammation and obesity." (PMID 22474520, 2012). "Furthermore, IL-6 upregulates vascular cell adhesion molecule-1 (VCAM-1) and intercellular adhesion molecule-1 (ICAM-1), facilitates T-cell differentiation, and enhances angiotensin II type 1 receptor expression in SMCs, exacerbating oxidative stress and endothelial dysfunction." (PMID 41375637, 2025). "Therefore, the elevated VCAM-1 observed in children and adolescents may reflect the known role of VCAM-1 in obesity-induced endothelial dysfunction and angiogenesis rather than NASH fibrosis per se." (PMID 31291245, 2019). "We further found that, although inducing endothelial cell dysfunction with TNFα or placental factors were associated with rising VCAM-1, when GATA2 was silenced in healthy cells, VCAM-1 was down regulated suggesting GATA2 may not be causal of endothelial dysfunction." (PMID 30659233, 2019). "We also report a lack of association between sCD163 and VCAM–1 for the first time in a SSA clinical cohort, replicating what has been observed in non–African cohorts, and we corroborate a previously demonstrated lack of association between IL–6 and cIMT with endothelial dysfunction in this setting." (PMID 29771268, 2018). "Moreover, VCAM-1 but not intercellular adhesion molecule-1 (data not shown), endothelin, or E-selectin were significantly diminished in the group with high miR-126 compared with low miR-126 expression, reflecting less endothelial dysfunction." (PMID 27127202, 2016). "Inflammatory markers (TNF-α, IL-6, hsCRP) and endothelial dysfunction markers (E-selectin, ICAM-1, VCAM-1) between MetS and non-MetS patients by gender." (PMID 31550292, 2019). "This study highlights the involvement of adhesion molecules (VCAM-1, ICAM-1, and E-Selectin) in the endothelial dysfunction of SCD patients with and without complications." (PMID 29690499, 2018). "However, in the current study, we observed no changes in the expression of ET-1, VCAM1, or ICAM1 in TNFα induced endothelial dysfunction in HUVECs when treated with 10 mU/mL of insulin for 24 h." (PMID 37893034, 2023).
endothelial dysfunction (continued). "Markers of endothelial dysfunction, ICAM-1 and VCAM-1, were both increased in ESRD patients lacking GSTM1, while ICAM-1 was upregulated in endothelial cells with a low level of GSTM1 exposed to uremic serum, further strengthening their potential biomarker role as predictors of CVD in ESRD patients." (PMID 33574979, 2021).